CARM1 (coactivator associated arginine methyltransferase 1)
Description:
Methylates (mono- and asymmetric dimethylation) the guanidino nitrogens of arginyl residues in several proteins involved in DNA packaging, transcription regulation, pre-mRNA splicing, and mRNA stability. Recruited to promoters upon gene activation together with histone acetyltransferases from EP300/P300 and p160 families, methylates histone H3 at 'Arg-17' (H3R17me), forming mainly asymmetric dimethylarginine (H3R17me2a), leading to activation of transcription via chromatin remodeling. During nuclear hormone receptor activation and TCF7L2/TCF4 activation, acts synergically with EP300/P300 and either one of the p160 histone acetyltransferases NCOA1/SRC1, NCOA2/GRIP1 and NCOA3/ACTR or CTNNB1/beta-catenin to activate transcription (By similarity). During myogenic transcriptional activation, acts together with NCOA3/ACTR as a coactivator for MEF2C (By similarity). During monocyte inflammatory stimulation, acts together with EP300/P300 as a coactivator for NF-kappa-B (By similarity). Acts as a coactivator for PPARG, promotes adipocyte differentiation and the accumulation of brown fat tissue (By similarity). Plays a role in the regulation of pre-mRNA alternative splicing by methylation of splicing factors (By similarity). Methylates EP300/P300, both at 'Arg-2142', which may loosen its interaction with NCOA2/GRIP1, and at 'Arg-580' and 'Arg-604' in the KIX domain, which impairs its interaction with CREB and inhibits CREB-dependent transcriptional activation. Also methylates arginine residues in RNA-binding proteins PABPC1, ELAVL1 and ELAV4, which may affect their mRNA-stabilizing properties and the half-life of their target mRNAs (By similarity). Acts as a transcriptional coactivator of ACACA/acetyl-CoA carboxylase by enriching H3R17 methylation at its promoter, thereby positively regulating fatty acid synthesis (By similarity). Independently of its methyltransferase activity, involved in replication fork progression: promotes PARP1 recruitment to replication forks, leading to poly-ADP-ribosylation of chromatin at replication forks and reduced fork speed.
Synonyms: PRMT4
Tractability: Small molecule: a structure with a bound ligand is known; a high-quality ligand is known; it has a high-quality binding pocket; it belongs to a druggable protein family. PROTAC: UniProt records ubiquitination sites on it; ubiquitination databases record sites on it; its protein half-life has been measured; a small molecule that binds it is known.
Target class: Epigenetic regulator; Protein arginine methyltransferase; Writer; Protein methyltransferase
Chemical probes: MS023 (high quality), MS049 (high quality), SKI-73 (high quality), TP-064 (high quality)
Gene: Protein-coding gene on chromosome 19 (10,871,553 to 10,923,075, forward strand). Ensembl gene ENSG00000142453.
Subcellular location: Nucleus; Cytoplasm; Chromosome
Subcellular location (Human Protein Atlas): Nucleoplasm
Pathways (Reactome):
Circadian clock: BMAL1:CLOCK,NPAS2 activates circadian expression; Expression of BMAL (ARNTL), CLOCK, and NPAS2; RORA,B,C and NR1D1 (REV-ERBA) regulate gene expression
Metabolism: Activation of gene expression by SREBF (SREBP); PPARA activates gene expression; Regulation of lipid metabolism by PPARalpha
Cellular responses to stimuli: Cytoprotection by HMOX1; Heme signaling
Chromatin organization: RMTs methylate histone arginines
Developmental Biology: Transcriptional regulation of white adipocyte differentiation
Organelle biogenesis and maintenance: Transcriptional activation of mitochondrial biogenesis
Signal Transduction: Estrogen-dependent gene expression
Gene Ontology:
Molecular function: DNA-binding transcription factor binding; histone H3R17 methyltransferase activity; histone H3R2 methyltransferase activity; histone methyltransferase activity; protein binding; protein methyltransferase activity; protein-arginine N-methyltransferase activity; protein-arginine omega-N asymmetric methyltransferase activity; transcription coactivator activity; beta-catenin binding; transcription cis-regulatory region binding
Biological process: positive regulation of epithelial cell apoptotic process; positive regulation of transcription by RNA polymerase I; replication fork reversal; positive regulation of fat cell differentiation; regulation of DNA-templated transcription; regulation of intracellular estrogen receptor signaling pathway; chromatin remodeling; negative regulation of dendrite development; positive regulation of cell population proliferation; response to cAMP
Cellular component: chromosome; cytoplasm; nuclear replication fork; nucleoplasm; nucleus; cytosol
Genetic constraint (gnomAD): Loss-of-function variants: 13 observed, 58.63 expected, observed/expected ratio (o/e) 0.22, 90% interval 0.14 to 0.35. The upper end of that interval is the gene's LOEUF score, 0.35, which puts it in group 1 of 6, group 1 being the genes least tolerant of losing a copy. Missense variants: 414 observed, 766.38 expected, observed/expected ratio (o/e) 0.54, 90% interval 0.5 to 0.59. Synonymous variants: 316 observed, 319.21 expected, observed/expected ratio (o/e) 0.99, 90% interval 0.9 to 1.09.
Homologues: Orthologues: chimpanzee CARM1 (99% identical), macaque CARM1 (99% identical), dog CARM1 (98% identical), mouse Carm1 (97% identical), rat Carm1 (97% identical), guinea pig CARM1 (89% identical), pig CARM1 (88% identical), tropical clawed frog carm1 (83% identical), zebrafish carm1 (81% identical), rabbit CARM1 (75% identical), Drosophila melanogaster Art4 (47% identical), Drosophila melanogaster Art2 (18% identical). Paralogues in human: PRMT3 (21% identical), PRMT8 (21% identical), PRMT1 (20% identical), PRMT2 (20% identical), PRMT6 (19% identical), PRMT9 (17% identical), PRMT7 (14% identical).
Diseases named in the same sentence as CARM1 in open-access papers:
CARM1 is named in the same sentence as 138 diseases in open-access papers, as found by Europe PMC text mining. Sharing a sentence is not in itself a finding about the gene and the disease. The quoted sentences say what the papers report.
breast carcinoma (76 papers, 2009 to 2026). "Among the implicated methyltransferases, CARM1 (PRMT4) is one of the best characterized in breast cancer." (PMID 41516402, 2026). "focused on the high expression of CARM1 in ERα‐positive breast cancer and its association with poor prognosis." (PMID 39964832, 2025). "A notable mechanism involves the asymmetric arginine methylation of BRG1-associated factor 155 (BAF155), a SWI/SNF core subunit and CARM1 substrate, which shows elevated levels in human breast cancer." (PMID 39922487, 2025). "It has been demonstrated that CARM1 upregulation is associated with the pathogenesis of several types of human cancers, including breast cancer, prostate cancer and colorectal cancer, and CARM1 facilitates tumor cell initiation, progression and metastasis." (PMID 35593475, 2022). "DZIP3 is known to bind to the coactivator-associated arginine methyltransferase 1 (CARM1) protein, which promotes oestrogen receptor α-mediated transcription in breast cancer." (PMID 35993275, 2022). "Significantly, highly expressed CARM1 is linked to poor prognosis for estrogen receptor (ER) positive subgroup of breast cancer cases." (PMID 35033016, 2022). "In breast cancer, coactivator-associated arginine methyltransferase 1 (CARM1) methylates pyruvate kinase M2 isoform (PKM2) to accelerate aerobic glycolysis, promoting breast tumorigenesis." (PMID 35892859, 2022). "The epigenetic upregulation of CCNE1 and E2F1 mediated by CARM1 is associated with the development of breast cancer." (PMID 34006904, 2021). "CARM1 (coactivator-associated arginine methyltransferase 1) is overexpressed in breast cancer to stimulate cell growth." (PMID 30845728, 2019). "For example, expression of CARM1 varies widely among different molecular subtypes of breast cancer, and overexpression of CARM1 is associated with invasive cancer and a poor prognosis." (PMID 24739482, 2014). "Our study demonstrated that CARM1 overexpression in breast cancer was associated with the overexpression of HER2." (PMID 23915145, 2013). "Aberrant expression of CARM1 has been linked to human breast cancer tissue in a few reports; however, current studies are contradictory and incomplete." (PMID 23915145, 2013). "In cancer biology, CARM1 has been implicated in various malignancies, with particular emphasis on its role in estrogen-induced proliferation in breast cancer cells." (PMID 39922487, 2025). "In breast cancer, coactivator-associated arginine methyltransferase 1 (CARM1)-mediated methylation of PKM2 promotes its interaction with inositol 1,4,5-trisphosphate receptors (InsP3Rs), reducing endoplasmic reticulum to mitochondria Ca2+ flux and triggering aerobic glycolysis." (PMID 40842995, 2025). "In addition, these mice display an increased incidence of both spontaneous mammary tumors and skin tumors with median onset >20 months, suggesting that CARM1 overexpression predisposes epithelial tissues to transformation." (PMID 37536629, 2023). "Additionally, CARM1 is a high-risk gene in breast cancer (OS, P = 0.019; DMFS, P = 0.00033; PPS, P = 0.0038), while it is a low-risk gene in liver cancer (DSS, P = 0.04; RFS, P = 0.033; PFS, P = 0.013)." (PMID 35033016, 2022). "A physical association of Sox2 with co-activator associated arginine methyltransferase 1 (CARM1) has been reported for murine embryonal carcinoma P19 cells, and CARM1-imposed Sox2 methylation at residue Arg113 further investigated in breast carcinoma MCF7 cells." (PMID 31477842, 2020). "Replacement of the native CARM1 with its catalytically dead mutant or with an Arg-to-Lys point mutation at the Arg1064 methylation site of BAF155 is sufficient to abolish the invasive capability of breast cancer cells." (PMID 31657716, 2019). "CARM1 has been reported to be associated with high grade tumors in breast cancer." (PMID 23915145, 2013). "We enabledantibody-free monitoring of CARM1 levels by fusing a HiBiT tag toCARM1 in MCF7 breast cancer cells." (PMID 41453375, 2026).
breast carcinoma (continued). "Fortriple-negative breast cancer, CARM1 represents a compelling therapeutictarget given its overexpression and its role in promoting metastasisand immune evasion." (PMID 41453375, 2026). "Frietze's early research identified CARM1 as a key factor in the oestrogen‐stimulated breast cancer growth pathway, downstream of ERα and AIB1 and upstream of the cell cycle regulatory transcription factor E2F1." (PMID 39964832, 2025). "The knockdown of CARM1 or PI3KC2α in breast cancer MCF7 cells significantly inhibited cell proliferation, cell survival, and DNA synthesis." (PMID 40045375, 2025). "Methylation of BAF41 positively regulates the expression of the c-Myc pathway, and CARM1/PRMT4 facilitates breast cancer metastasis by methylating the arginine residue R155 of the chromatin remodeling factor BAF1064." (PMID 41154773, 2025). "Targeting CARM1-mediated GATAD2A/2B methylation with CARM1 specific inhibitors potently inhibit breast cancer cell growth in vitro and tumorigenesis in vivo." (PMID 38676947, 2024). "Taken together, our data suggested that targeting CARM1 is effective in inhibiting breast cancer cell growth both in vitro and in vivo." (PMID 38676947, 2024). "Coactivator-associated arginine methyltransferase 1 (CARM1) promotes the development and metastasis of estrogen receptor alpha (ERα)-positive breast cancer." (PMID 38476024, 2024). "CARM1’s function in breast cancer is, at least partially, mediated through its methyltransferase activity targeting GATAD2A." (PMID 38676947, 2024). "Using the human cancer survey RT-qPCR gene expression panel in breast tissue, we observed that CARM1 was highly expressed in breast cancer samples compared with normal tissues." (PMID 38476024, 2024). "The clinical relevance of CARM1-mediated GATAD2A methylation in cell cycle control is further illustrated in breast cancer, where higher expression of CARM1 and GATAD2A is observed compared to normal tissues." (PMID 38676947, 2024). "Subsequently, correlation analysis of breast cancer in TCGA indicated that the expression of CARM1 is positively correlated with that of HIF1A and CDK4." (PMID 38476024, 2024). "To further determine the expression of CARM1 in basal-like breast cancers, we analyzed published clinical data from GSE104549." (PMID 38476024, 2024). "According to the Cancer Genome Atlas (TCGA) database, CARM1 was highly expressed in basal-like breast cancer." (PMID 38476024, 2024). "We demonstrated that CARM1-mediated GATAD2A methylation was important for the growth of breast cancer cells both in vitro and in vivo." (PMID 38676947, 2024). "From the GEO DataSets GSE42568, we found that PRMT1, PRMT2, and CARM1 were highly expressed in breast cancer cells." (PMID 38476024, 2024). "As previously reported, CARM1 enhances breast cancer progression and metastasis in ERα-positive breast cancer and is a co-activator of ERα." (PMID 38476024, 2024). "CARM1 substrates, such as E2F1, BAF155 and MED12, were suggested to be important for CARM1-mediated breast cancer cell growth and tumorigenesis." (PMID 38676947, 2024). "For gain-of-function, breast cancer cells were infected with lentivirus delivering CARM1 CDS (coding sequence); and for loss-of-function, breast cancer cell lines with stably depleted CARM1 were generated using three different lentivirus-delivered shRNAs." (PMID 38476024, 2024). "In contrast, knockout of CARM1 induced drug resistance in breast cancer cell lines whereas high CARM1 expression in breast cancer patients increased their overall survival after adjuvant chemotherapy." (PMID 39703687, 2024). "Due to the fact that they are highly expressed in breast tumor samples and their high expression predict poor prognosis in patients with breast cancer, the pathological relevance of CARM1 and NuRD was investigated." (PMID 38676947, 2024).
breast carcinoma (continued). "In breast cancer cells, treatment with a CARM1 inhibitor or expression of a CARM1-methylation-resistant LSD1 mutant inhibited cell migration and invasion." (PMID 39394462, 2024). "Compared with that in normal tissues, the expression of CDK4, HIF1A, and MALAT1 were upregulated in the breast cancer samples, which was consistent with the results of CARM1." (PMID 38476024, 2024). "Conversely, overexpression of CARM1 or LSD1 in breast cancer cells promoted cell migration and invasion." (PMID 39394462, 2024). "We focused on breast cancer in the current study as numerous studies including ours showed that CARM1 plays a critical role in breast cancer development." (PMID 38676947, 2024). "CARM1 is upregulated in multiple cancers and its expression correlates with breast cancer progression." (PMID 38476024, 2024). "Taken together, our data suggested that CARM1-mediated GATAD2A methylation is involved in breast cancer cell growth and tumorigenesis." (PMID 38676947, 2024). "The clinical significance of this gene activation mechanism is underscored by the high expression of CARM1 and NuRD in breast cancers, and the fact that knockdown CARM1 and NuRD inhibits cancer cell growth in vitro and tumorigenesis in vivo." (PMID 38676947, 2024). "For instance, CARM1 is found to be overexpressed in breast cancer and prostate carcinoma, mediator complex subunit 19 (MED19) is upregulated in bladder cancer, and nuclear receptor co-activator 5 (NCOA5) expression is elevated in colorectal cancer." (PMID 39343952, 2024). "For example, overexpression of CARM1, an epigenetic enzyme and co-transcriptional activator, has been reported to predict poor prognosis in breast cancer and non-small cell lung cancer." (PMID 37894336, 2023). "Methylation of pyruvate kinase isoform M2 (PKM2) by CARM1 transforms the metabolism of breast cancer cells from OXPHOS to aerobic glycolysis." (PMID 37649137, 2023). "For example, the effect of CARM1 expression on prognosis in breast cancer is related to the state of HER2." (PMID 35033016, 2022). "As a coactivator of the estrogen receptor ERα, CARM1 regulates estrogen-dependent breast cancer cell proliferation and differentiation." (PMID 34006904, 2021). "CARM1 suppresses estradiol (E2)-dependent cell cycle progression and proliferation of breast cancer cells via modulation of the ERα-mediated transcription of proteins, especially p21WAF1, p27KIP1, Cyclin G2, MAZ, KRTAP10.12, and GATA-3." (PMID 34006904, 2021). "In ER-positive breast cancers, the expression level of CARM1 is positively correlated with ERα levels and inversely correlated with tumor grade, suggesting that CARM1 is a biomarker of well-differentiated breast cancer cells." (PMID 34006904, 2021). "CARM1/PRMT4 has been well studied in terms of its association with lung and breast cancer and, more recently, implicated in the development of GBM." (PMID 33440687, 2021). "Regarding CARM1, its increased expression corresponds with a less favorable prognosis in breast cancer and with HER2-positive tumors." (PMID 34663249, 2021). "CARM1 is recruited at the E2F1 promoter in breast cancer, which upregulates E2F1 expression and alters the expression of downstream cell cycle-related proteins, promoting the proliferation of breast cancer cells." (PMID 34745258, 2021). "It has been reported that CARM1 is overexpressed in multiple cancers and regulates chemoresistance of cancer cells through arginine methylation, such as in breast cancer and pancreatic cancer." (PMID 33495408, 2021). "PRMT1 also regulates EMT in breast cancer cells while CARM1/PRMT4 promotes breast cancer metastasis by methylating arginine residue R1064 of BAF155, a chromatin remodeling factor." (PMID 33440687, 2021). "Using MCF7 breast cancer cell line as a model system, we demonstrated that cell proliferation rate was decreased significantly and cells were arrested in G1 phase when CARM1 was knocked down." (PMID 32206101, 2020).